RNU1-150P (RNA, U1 small nuclear 150, pseudogene)
Gene: Small nuclear RNA gene on chromosome 5 (40,269,558 to 40,269,719, forward strand). Ensembl gene ENSG00000199361.
Homologues: Orthologues: chimpanzee U1 (99% identical), macaque U1 (91% identical), pig U1 (78% identical). Paralogues in human: RNU1-1 (84% identical), RNU1-2 (84% identical), RNU1-27P (84% identical), RNU1-28P (84% identical), RNU1-3 (84% identical), RNU1-4 (84% identical), RNVU1-18 (84% identical), RNVU1-29 (84% identical), RNVU1-32 (84% identical), U1 (84% identical), RNVU1-28 (83% identical), RNVU1-31 (83% identical), and 134 more.